CNOT2 (CCR4-NOT transcription complex subunit 2)
Description:
Component of the CCR4-NOT complex which is one of the major cellular mRNA deadenylases and is linked to various cellular processes including bulk mRNA degradation, miRNA-mediated repression, translational repression during translational initiation and general transcription regulation. Additional complex functions may be a consequence of its influence on mRNA expression. Required for the CCR4-NOT complex structural integrity. Can repress transcription and may link the CCR4-NOT complex to transcriptional regulation; the repressive function may specifically involve the N-Cor repressor complex containing HDAC3, NCOR1 and NCOR2. Involved in the maintenance of embryonic stem (ES) cell identity.
Synonyms: CDC36; NOT2; HSPC131; NOT2H; IDNADFS
Tractability: Antibody: its Gene Ontology location is reachable by antibodies, with high confidence. PROTAC: ubiquitination databases record sites on it; its protein half-life has been measured.
Gene: Protein-coding gene on chromosome 12 (70,243,002 to 70,354,993, forward strand). Ensembl gene ENSG00000111596.
Subcellular location: Cytoplasm; Nucleus
Subcellular location (Human Protein Atlas): Nucleoplasm; Cytosol
Pathways (Reactome):
Developmental Biology: M-decay: degradation of maternal mRNAs by maternally stored factors
Metabolism of RNA: Deadenylation of mRNA
Gene Ontology:
Molecular function: poly(A)-specific ribonuclease activity; protein binding; transcription corepressor binding; transcription coregulator activity
Biological process: negative regulation of intracellular estrogen receptor signaling pathway; negative regulation of transcription by RNA polymerase II; positive regulation of cytoplasmic mRNA processing body assembly; regulation of stem cell population maintenance; nuclear-transcribed mRNA poly(A) tail shortening; regulation of transcription by RNA polymerase II; regulation of DNA-templated transcription; trophectodermal cell differentiation
Cellular component: CCR4-NOT complex; cytoplasm; membrane; CCR4-NOT core complex; cytosol; nucleus; P-body
Genetic constraint (gnomAD): Loss-of-function variants: 2 observed, 29.89 expected, observed/expected ratio (o/e) 0.0669, 90% interval 0.026 to 0.21. The upper end of that interval is the gene's LOEUF score, 0.21, which puts it in group 1 of 6, group 1 being the genes least tolerant of losing a copy. Missense variants: 133 observed, 280 expected, observed/expected ratio (o/e) 0.47, 90% interval 0.41 to 0.55. Synonymous variants: 88 observed, 101.69 expected, observed/expected ratio (o/e) 0.87, 90% interval 0.73 to 1.03.
Homologues: Orthologues: chimpanzee CNOT2 (100% identical), macaque CNOT2 (100% identical), mouse Cnot2 (99% identical), rat Cnot2 (99% identical), pig CNOT2 (99% identical), rabbit CNOT2 (99% identical), guinea pig CNOT2 (97% identical), tropical clawed frog cnot2 (94% identical), zebrafish cnot2 (85% identical), dog CNOT2 (53% identical), Drosophila melanogaster Rga (36% identical), Caenorhabditis elegans ntl-2 (28% identical), and 1 more. Paralogues in human: CNOT3 (24% identical).
Diseases named in the same sentence as CNOT2 in open-access papers:
CNOT2 is named in the same sentence as 37 diseases in open-access papers, as found by Europe PMC text mining. Sharing a sentence is not in itself a finding about the gene and the disease. The quoted sentences say what the papers report.
breast carcinoma (9 papers, 2014 to 2025). "A previous study reported that CNOT2 deficiency in breast cancer inhibited cell proliferation and angiogenesis via VEGF signaling." (PMID 37550432, 2023). "Recently, a CNOT2-centered transcriptional network module was reported to be relevant for the susceptibility of breast cancer to metastasis." (PMID 25191340, 2014). "CNOT2 was found to be overexpressed in breast cancer cell lines (MCF-7 and MDA-MB-231), promoting tumor proliferation and metastasis." (PMID 40864769, 2025). "Given its regulatory involvement in tumor proliferation, angiogenesis, and metastasis, CNOT2 emerges as a potential therapeutic target for breast cancer." (PMID 40864769, 2025). "Recent studies in our laboratory showed that CNOT2 promotes breast cancer cell proliferation and angiogenesis." (PMID 34680125, 2021). "Downregulation of Cnot2 expression results in a significant increase of breast cancer pulmonary metastasis in vivo." (PMID 30144809, 2018). "These miRNAs may serve as downstream effectors of CNOT2, acting as regulatory nodes in breast cancer cell migration and EMT." (PMID 40864769, 2025). "Moreover, our studies show that the inhibition of CNOT2 expression regulates EMT in breast cancer cells." (PMID 34680125, 2021). "CNOT2 also regulates the metastasis of murine breast cancer in a mouse xenograft model." (PMID 25191340, 2014). "Additionally, CNOT2 has been reported to promote breast cancer cell proliferation and angiogenesis." (PMID 40864769, 2025). "In primary breast cancers, circRNAs of CREBBP, CNOT2, and RERE and RNAi-mediated knockdown of circRNA circCNOT2 was shown to significantly reduce the viability of two breast cancer cell lines: MCF-7 and BT-474." (PMID 32467674, 2020). "Moreover, CNOT2 can also inhibit the ligand-dependent transcriptional activation of ERα and retinoid X receptor (RXR) target genes such as c-Myc in MCF-7 human breast cancer cells." (PMID 40864769, 2025). "Studies from a breast cancer mouse model and human patient data demonstrate a negative correlation between CNOT2 expression and tumor development and the CCR4-NOT complex was implicated in tumor cell metastasis." (PMID 31724941, 2019). "Generation of co-expressed gene maps from mouse strains with differing inherited sensitivity for pulmonary metastasis identified a network module centered on the CCR4-NOT component Cnot2 that was capable of discriminating breast cancer patient outcome." (PMID 26807845, 2016).
liver cancer (7 papers, 2020 to 2025). An epithelial or non-epithelial malignant neoplasm that arises from the liver. "MID1IP1 supports the cooperation of proto-oncogene c-Myc, mediated by RPL5, RPL11, and CNOT2, which acts as a potent oncogene molecule, in the progression of liver cancer." (PMID 40864769, 2025). "And there have also been studies suggesting that liver cancer growth can regulate c-Myc in the liver, mediated by CNOT2." (PMID 40864769, 2025). "Taken together, these findings provide novel insight that MID1IP1 promotes the growth of liver cancer via colocalization with c-Myc mediated by ribosomal protein L5 and L11 and CNOT2 as a potent oncogenic molecule." (PMID 32316188, 2020). "Overall, these findings provide novel insight that MID1IP1 promotes the growth of liver cancer via colocalization with c-Myc mediated by ribosomal proteins L5 and L11 and CNOT2 as a potent oncogenic molecule." (PMID 32316188, 2020). "Overall, these findings suggest that MID1IP1 promotes liver cancer progression via colocalization with c-Myc mediated by ribosomal protein L5 and L11 and CNOT2 as a potent oncogenic molecule." (PMID 32316188, 2020). "In hepatocellular carcinoma cell lines (HepG2 and Huh7), CNOT2 deficiency was found to enhance the antitumor effects of MID1IP1 depletion while reducing apoptosis markers, suggesting a functional interplay between CNOT2 and MID1IP1 in liver cancer cells." (PMID 40864769, 2025). "Furthermore, c-Myc signaling mediated by CNOT2 and the ribosomal proteins L5 or L11 regulate cell growth in hepatic cancer cells." (PMID 37550432, 2023). "In a previous study, liver cancer growth was shown to regulate liver c-Myc mediated by CNOT2." (PMID 37550432, 2023). "Our previous paper showed that CNOT2 regulates liver cancer cell growth through c-Myc and MID1IP1." (PMID 36569330, 2022). "Furthermore, MID1IP1 regulates liver cancer growth through c-Myc mediated by CNOT2." (PMID 36233202, 2022). "We also previously reported that the simultaneous knockdown of CNOT2 and MID1IP1 in colorectal and liver cancer cells contributes to cancer cell growth and apoptosis by significantly inhibiting c-Myc expression." (PMID 36569330, 2022). "CNOT2, MID1IP1, and Pin1 genes are overexpressed in cancer cells of various organs, such as colorectal cancer and liver cancer, promoting tumor growth and metastasis, and commonly regulating the expression of c-Myc." (PMID 36569330, 2022). "Furthermore, depletion of CNOT2 was shown to enhance the antitumor effect of midline 1 interacting protein 1 (MID1IP1) depletion, thus inhibiting c-Myc expression in liver cancer cells." (PMID 34680125, 2021). "Furthermore, CNOT2 is related to c-Myc, which is mediated by the ribosomal proteins L5, L11, or by midline 1 interacting protein 1 (MID1IP1) in liver cancer cells." (PMID 34680125, 2021).
colon cancer (6 papers, 2021 to 2023). "On the basis of this information, we found that CNOT2 knockdown by siRNA is related to decreased colon cancer cell viability." (PMID 34680125, 2021). "The survival rate was significantly increased in colon cancer patients with low CNOT2 expression as compared with patients with high expression." (PMID 34680125, 2021). "Thus, to the best of our knowledge, this study is the first to reveal that TA3-induced apoptosis through c-Myc requires CNOT2 or MID1IP1 in colon cancer cells." (PMID 36233202, 2022). "Furthermore, CNOT2 knockdown enhanced the inhibitory effect of OP-D on c-Myc in colon cancer cells." (PMID 36569330, 2022). "We identified changes in protein expression levels of oncogenes such as CNOT2 and MID1IP1 when ES was treated in colon cancer cells through Western blotting." (PMID 37110707, 2023). "Combination treatment also increased apoptosis and further reduced expression of the oncogenes c-Myc, CNOT2, and MID1IP1 in colon cancer cells." (PMID 38139419, 2023). "The protein expression of c-Myc, CNOT2, and MID1IP1 decreased in a dose- and time-dependent manner after ACN treatment of colon cancer cells." (PMID 38139419, 2023). "In this study, we confirmed that ACN induces apoptosis by negatively regulating oncogenes, including c-Myc, CNOT2, and MID1IP1, in various colon cancer cells." (PMID 38139419, 2023). "Therefore, we confirm that ES has anticancer effects by inducing apoptotic cell death and regulating the oncogenes CNOT2 and MID1IP1, suggesting its potential for use in the treatment of colon cancer." (PMID 37110707, 2023). "Altogether, our results reveal a mechanism by which TA3 induces apoptosis through inhibiting c-Myc expression via CNOT2 or MID1IP1 in HCT116, which may help in the development of new therapies for colon cancer based on TA3 in the future." (PMID 36233202, 2022). "However, there is no paper on the specific role of CNOT2 in colon cancer yet." (PMID 34680125, 2021).
colorectal cancer (6 papers, 2020 to 2025). A primary or metastatic malignant neoplasm that affects the colon or rectum. "In addition, it has been reported that the simultaneous knockdown of MID1IP1 and CNOT2 in the liver and in colorectal cancer cells further downregulates c-Myc, thereby contributing to cancer cell growth and apoptosis." (PMID 36233202, 2022). "Moreover, a follow-up study is planned to further investigate the anti-cancer mechanism of TA3 in colorectal cancer in relation to whether TA3 binds directly to CNOT2 and MID1IP1 to interfere with expression." (PMID 36233202, 2022). "Furthermore, based on previous research, we established that the inhibition of CNOT2 induces apoptosis via reductions in MID1IP1 and c-Myc, and we thus investigated whether CS&Z regulates the expression of the oncogenes MID1IP1 and CNOT2 in colorectal cancer cells." (PMID 40429805, 2025). "Our results indicate that TA3 suppresses the expression of c-Myc via downregulation of CNOT2 and MID1IP1 in colorectal cancer cell lines, thereby inducing apoptotic markers." (PMID 36233202, 2022). "Building upon these findings, we targeted c-Myc in colorectal cancer cells using CS&Z, and accordingly detected a reduction in c-Myc protein levels, which was accompanied by apoptotic changes in the protein levels of PARP, caspase 3, CNOT2, and MID1IP1." (PMID 40429805, 2025). "Therefore, this study focused on controlling the expression of c-Myc in various colorectal cancer cells, and further, an experiment was conducted focusing only on tumor genes c-Myc, MID1IP1, and CNOT2 using HCT116p53+/+." (PMID 36233202, 2022). "Furthermore, CNOT2 knockdown enhanced the inhibitory effect of MID1IP1 depletion on c-Myc and pro-PARP, even in HCT116 colorectal cancer cells." (PMID 32316188, 2020).
non-small cell lung carcinoma (4 papers, 2019 to 2025). A group of at least three distinct histological types of lung cancer, including non-small cell squamous cell carcinoma, adenocarcinoma, and large cell carcinoma. "Previous studies have demonstrated that CNOT2 plays a critical role in atorvastatin-induced apoptosis in non-small cell lung cancer cells." (PMID 40864769, 2025). "Although how CNOT2 and CNOT3 function in the catalytic subunit during the oral cancer process remains unclear, a mutation in CNOT3 is associated with non-small cell lung cancer and T-cell acute lymphoblastic leukemia." (PMID 31724941, 2019). "The leading genes contributing towards a higher targeting of RNA degradation among males include CNOT1, CNOT2, CNOT3 and DCP1A, all of which have previously been found to have prognostic significance in various cancers, including non-small cell lung cancer." (PMID 39107837, 2024).
lung carcinoma (2 papers, 2021 to 2023). "According to a recent paper, CNOT2 is associated with lung cancer cells." (PMID 34680125, 2021). "In addition, CNOT2 involved with atorvastatin induced both apoptotic and autophagic cell death in lung cancer cells." (PMID 34680125, 2021). "In addition, CNOT2 signals are critically related to apoptosis induced by atorvastatin in lung cancer cells." (PMID 34680125, 2021). "Therefore, CNOT4 and CNOT2 may be stable reference genes for lung cancer cells under these five conditions." (PMID 37274277, 2023).
pancreatic cancer (2 papers, 2023 to 2025). "Furthermore, it was observed that CNOT2, which primarily acts as an oncogene in various cancers, also functions as an oncogene in pancreatic cancer and is associated with migration." (PMID 37550432, 2023). "CNOT2 and c-Myc were proportionally associated with pancreatic cancer." (PMID 37550432, 2023). "In tumor tissue, CNOT2 is overexpressed, and in pancreatic cancer, CNOT2 regulates the expression of c-Myc." (PMID 40864769, 2025). "We investigated the expression levels of the CNOT2 gene in adjacent normal and tumor tissues in pancreatic cancer using the Cancer Genome Atlas (TCGA) website." (PMID 37550432, 2023). "In this study, we evaluated the anticancer effects of the MS extract through the regulation of c-Myc and CNOT2 in pancreatic cancers." (PMID 37550432, 2023). "Using this tool, a correlation analysis between CNOT2 gene expression pattern and pancreatic cancer patient survival rate was conducted, revealing that higher CNOT2 expression is associated with lower survival rate." (PMID 37550432, 2023). "The association between the expression of CNOT2 and MYC and the characteristics of pancreatic tumors was confirmed using TCGA analysis." (PMID 37550432, 2023). "Therefore, CNOT2 can be considered an important genetic marker in the treatment and prognosis evaluation of pancreatic cancer." (PMID 37550432, 2023). "Immunoblotting was performed using pancreatic cancer cells to confirm whether the MS extract regulates c-Myc and CNOT2." (PMID 37550432, 2023). "Furthermore, the MS extract increased apoptosis by regulating c-Myc and CNOT2 expression and enhanced the sensitivity of 5-FU in pancreatic cancer." (PMID 37550432, 2023). "Additionally, CNOT2 was proportionally related to migration-related factors in pancreatic cancer, and the MS extract inhibited migration through CNOT2." (PMID 37550432, 2023).
B cell lymphoma (1 paper, 2017). "Upregulation of MHC II genes did not occur after knock-out of CNOT3 in T cells (data not shown) or after knock-down of CNOT2 in Raji B cell lymphoma cells." (PMID 28615693, 2017).
brain tumor (1 paper, 2023). "Down-regulated DEGs in recGBM included genes involved in cell proliferation (EGFR), possibly brain tumor cell growth (BCAN), deadenylation of mRNA, which is linked to neurodevelopmental disorders (CNOT2), and multi-drug resistance (ABCG2)." (PMID 37189838, 2023). "Down-regulated DEGs in recGBM were involved in cell proliferation (EGFR) and possibly brain tumor cell growth (BCAN), deadenylation of mRNA, which is linked to neurodevelopmental disorders (CNOT2), multi-drug resistance (ABCG2), and immune-related processes (GZMK)." (PMID 37189838, 2023).
Dengue virus infection (1 paper, 2022). "Furthermore, CNOT2 supports Dengue virus infection by inhibiting JAK-STAT antiviral signaling via its interaction with CNOT6/6L and CNOT7/8 deadenylases." (PMID 36140672, 2022).
developmental delays (1 paper, 2021). "The heterozygous intragenic deletion of CNOT2 displayed disordered phenotypes including learning disabilities, developmental delays, and hypothyroidism." (PMID 33888058, 2021).
hepatocellular carcinoma (1 paper, 2025). A malignant tumor that arises from hepatocytes. "Furthermore, researchers studied the oncogenic potential of MID1IP1 in hepatocellular carcinoma cell (HCC) growth in relation to ribosomal protein L5 and L11 and CNOT2-mediated c-Myc signaling and found that CNOT2 knockdown could further inhibit the downregulation of MID1IP1 by c-Myc." (PMID 40864769, 2025).